CD81 (CD81 molecule)
Diseases named in the same sentence as CD81 in open-access papers (continued):
Sharing a sentence is not in itself a finding about the gene and the disease.
hepatoma (continued). "The tetraspanin CD81 has been identified as interaction partner of the HCV envelope glycoprotein E2 and anti-CD81 mAbs, as well as a recombinant, soluble form of the large extracellular domain of CD81 inhibited the entry of HCV into hepatoma cell lines." (PMID 18836553, 2008). "CD81 was downregulated at the mRNA level in hepatoma cells that replicate HCV." (PMID 38357447, 2024). "The two most down-regulated proteins, CD63 and CD81, which is one of the HCV entry receptors, were independently confirmed upon electroporation of Huh7.5 hepatoma cells with a viral genome RNA encoding for a fluorescently labeled NS5A fusion protein (Jc1_NS5A-eGFP)." (PMID 38357447, 2024). "Indeed, low levels of CD81 correlate with HCC metastasis and tumor proliferation and expression of CD81 suppresses hepatocellular carcinoma development." (PMID 38357447, 2024). "A recent study pointed out that JNK signaling pathway may be involved in the growth suppression mediated by CD81 overexpression in hepatocellular carcinoma can cell." (PMID 38280104, 2024). "Here, we identify CD81 as repressor of NF-κB signaling in hepatoma and other cells." (PMID 38357447, 2024). "Similarly, we witnessed an overall increase in the total levels of phosphorylated and cellular p65 upon CD81-knockout in hepatoma cells." (PMID 38357447, 2024). "A proteomic analysis mapped 33 host protein interactions of CD81 in primary human liver and hepatoma cells, including for example protein CAPN5 (calpain-5) and ubiquitin ligase CBLB (Casitas B-lineage lymphoma proto-oncogene B), capable of forming a complex with CD81 and implicated in HCV entry." (PMID 37046846, 2023). "CD81 regulates HCV trafficking to the tight junction in polarized hepatoma spheroids." (PMID 38157366, 2023). "As CD9 is the closest homolog of CD81 and showed only low expression levels in hepatoma cells, but slightly higher expression levels in fibroblasts, we decided to investigate whether CD9 can also function as CHIKV host factor." (PMID 35612284, 2022). "The physiological function of CD81 in hepatoma cells is poorly defined." (PMID 32322956, 2020). "To unravel, whether the identified CD81 protein interaction network in hepatoma cells reflected the PPIs in primary human hepatocytes, we developed a second LFQ affinity enrichment mass spectrometry (AE-MS) pipeline." (PMID 30024968, 2018). "As prey protein enrichment was limited in the co-IPs from HA-tagged CD81 expressing cells, we performed a second overlap analysis exclusively with the primary hepatocyte hits (>4-fold enrichment) and highly significant hepatoma cell hits (FDR = 0.004, s0 = 2) from cells with untagged CD81." (PMID 30024968, 2018). "Finally, we report a whole cell proteome expression dataset for human hepatoma cells and show that CAPN5 is strongly associated with CD81." (PMID 30024968, 2018). "Therefore, we determined high stringency CD81 protein interactions in human hepatoma cells and primary human liver cells through analysis of 120 different CD81 co-immunoprecipitations (co-IP) and high-resolution quantitative mass spectrometry." (PMID 30024968, 2018). "However, when in a physiologically-relevant membrane (i.e. Huh-7.5 hepatoma cells), CD81 is displayed in a manner that alters epitope presentation, revealing nuances in mAb binding, which, in turn, determines the potency of anti-HCV activity." (PMID 29090272, 2017). "To evaluate whether the mAbs recognise cell-surface CD81, we screened the panel for reactivity with HepG2 hepatoma cells that lack CD81 and with cells transduced to express human CD8134." (PMID 29090272, 2017). "Interestingly, it has been very recently demonstrated that exosomes (which are enriched in tetraspanins such as CD81) from HCV-infected cells were capable of transmitting infection to naïve human hepatoma cells, in the presence of neutralizing antibodies." (PMID 24509809, 2014).
hepatoma (continued). "To further test this hypothesis, we monitored HCV infection in CD81 knock-out hepatoma cells (CD81−Huh7.5) that are resistant to cell-free entry and only display minimal levels of CD81-independent cell-cell transmission." (PMID 24830295, 2014). "In contrast, CD81 expression confers susceptibility to HCV infection in hepatoma cell lines lacking CD81, such as HepG2 cells." (PMID 24553110, 2014). "Our study highlights a role for CD81 in promoting the invasion and motility of hepatoma cell lines." (PMID 24662676, 2014). "Furthermore, silencing CD81 expression in Huh-7 hepatoma cells attenuated their invasive potential in vitro." (PMID 24662676, 2014). "In addition, a study based on a mathematical model of HCV viral kinetics in vitro evaluated that between one and thirteen CD81/E2 complexes are necessary for HCV entry into hepatoma-derived cells." (PMID 24509809, 2014). "HCV infection perturbs CD81-dependent hepatoma spread that may have important consequences for HCV associated HCC pathogenesis." (PMID 24662676, 2014). "In contrast, Mazzocca and colleagues reported that CD81 suppressed hepatoma motility in vitro." (PMID 24662676, 2014). "Hepatoma polarization reduced CD81 and HCVpp dynamics at the basal membrane." (PMID 23126643, 2013). "CD5 was displayed by HCV-prone T cell lines, primary T cells and PBMC, but not by non-susceptible T and hepatoma cell lines, while CD81 in all cell types except HepG2." (PMID 23626783, 2013). "Indeed, ectopic expression of EWI-2wint in an HCV-permissive hepatoma cell line inhibited viral entry by blocking HCV binding to CD81, most likely through interactions with CD81." (PMID 21193846, 2010). "Conversely, in HCV-expressing hepatoma cells, CD81 expression was downregulated, and CD81-knockout cells exhibited increased viral replication associated with enhanced pro-survival signaling, implying that CD81 may also contribute to viral persistence and chronic infection." (PMID 41157594, 2025). "Since we observed a strong dependency of CD81 in hepatoma cells and a milder effect in fibroblasts, we asked if the expression pattern of tetraspanin family members differs between the two cell types and if another tetraspanin may serve as a host factor in fibroblasts." (PMID 35612284, 2022). "To further analyze the role of human and mouse SR-B1, we took advantage of the fact that the murine hepatoma Hepa1-6 cells do not express SR-B14 and generated a variant cell line deficient for murine CD81 (CD81 knockout (KO) Hepa1-6 or CD81KOH16) using the CRISPR-Cas9 system." (PMID 32782257, 2020). "We recently reported a role for the CD81 C-terminus of CD81 and its association with the actin cytoskeleton via ERM proteins in CD81 lateral diffusion at the plasma membrane, supporting a dynamic interplay of CD81 with partner proteins and the actin cytoskeleton in defining hepatoma mobility." (PMID 24662676, 2014). "Beyond the head and neck, in hepatocellular carcinoma, tetraspanins CD9 and CD81 are tumor suppressive: CD81 is frequently lost in tumor tissue, and reduced CD9/CD81 expression correlates with advanced stage and poorer outcomes." (PMID 41322905, 2025). "Huh7.5 hepatoma cells harboring gene knock-outs in CD63 and CD81 were electroporated to express Jc1_R2A, and luciferase activity was measured as a proxy for viral genome replication and spread." (PMID 38357447, 2024). "According to a study on the expression of TSPANs in the Oncomine database about hepatocellular carcinoma, the expression of TSPAN7, TSPAN12 and TSPAN28 (CD81) proteins were lower in hepatocellular carcinoma cells than in normal liver tissue." (PMID 37752917, 2023). "EGCG boosted miR-548m expression, thereby downregulating both CD81 protein and mRNA levels in HCV-infected Huh7 human hepatoma cells." (PMID 37046846, 2023).
hepatoma (continued). "Almost half of these genes (purple-colored genes) were enriched in Hepatitis B, Hepatitis C and Hepatocellular carcinoma pathways including MYC, CD81, CDKN1A, IGF1R and so on which were reported in Hepatocellular carcinoma." (PMID 37051592, 2023). "In hepatocellular carcinoma (HCC), Klf4 was shown to regulate the expression of CD9/CD81, exosomal tetraspanin surface proteins that mediate cellular interaction and have been found to be involved in cancer." (PMID 34195082, 2021). "The binding of HCV to human hepatoma cells induces EGFR activation which is dependent on the interactions between HCV and CD81." (PMID 25757571, 2015). "Infection of Huh-7.5 hepatoma cells with HCV strains J6/JFH and SA13/JFH led to a significant reduction in CD81-dependent hepatoma spread." (PMID 24662676, 2014). "In summary, our data illustrate a role for CD81 in regulating hepatoma migration and invasion, which may impact on HCC metastasis." (PMID 24662676, 2014). "To investigate whether CD81 promotes hepatoma motility, we assessed the ability of HepG2 and Huh-7.5 cells to invade collagen I extracellular matrix and to migrate in a scratch wound assay, features that are considered to define hepatoma metastatic potential in vivo." (PMID 24662676, 2014). "In summary, these data highlight a role for the CD81 C-terminus and ERM proteins in promoting CD81-dependent hepatoma spread." (PMID 24662676, 2014). "The tetraspanin CD81 is an essential receptor for HCV, however, its role in hepatoma biology is uncertain." (PMID 24662676, 2014). "In summary, this study highlights the dynamic nature of CD81 and demonstrates a role for CD81 lateral diffusion in HCV infection of hepatoma cells that is dependent on their polarized status." (PMID 23126643, 2013). "In our study, we describe a human hepatoma Huh-7 cell clone (Huh-7w7) which has lost CD81 expression and can be infected by HCV when human CD81 (hCD81) or mouse CD81 (mCD81) is ectopically expressed." (PMID 19476617, 2009). "The ability to block infection of both HCVcc and HCVser with anti-CD81 antibodies demonstrates an important role of CD81 during infection of PHH and hepatoma cell lines." (PMID 19087224, 2008). "This suggests that the absence of CD81 can compensate for TBK1-mediated inhibition of proliferation of Huh7.5 hepatoma cells." (PMID 38357447, 2024). "Notably, hepatoma cells with GFP‐core protein expression presented with enhanced mRNA and protein levels of virus infection‐relevant receptors, including CD36, CD81, Claudin1, LDL R, and ACE2." (PMID 37316966, 2023). "In silico assessment of transcriptomic data within the cancer genome atlas (TCGA) database indicated high expression of CD9 and CD81 in all analyzed tumor sets, while expression of TSPAN8 was elevated in particular in hepatocellular carcinoma and colonic adenocarcinoma." (PMID 36078095, 2022). "From those described to play a role in virus infection, we determined the mRNA expression level in hepatoma cells lacking or expressing CD81 as well as in dermal fibroblasts." (PMID 35612284, 2022). "To map the CD81 PPI network in human hepatoma cells, we performed a total of 64 CD81 co-IPs in quadruplicates from Lunet cells lacking or expressing CD81." (PMID 30024968, 2018). "We show that a number of antibodies targeting linear and conformational CD81 epitopes in EC2 induce hepatoma spread, suggesting that this phenotype is independent of epitope or antibody binding affinity." (PMID 24662676, 2014). "Although our studies have identified a role for CD81 in hepatoma cell migration and invasion, anti-CD81 mAbs failed to modulate these processes suggesting limited therapeutic potential." (PMID 24662676, 2014). "Finally, it has been shown that CD81- and CD9-enriched membrane microdomains are implied in pDCs interaction with infected hepatoma cells and are likely involved in endocytosis of HCV components such as viral RNA." (PMID 24509809, 2014).
hepatoma (continued). "Given the importance of NF-κB for HCV replication and persistence, as well as its role in tumor development and hepatocellular carcinoma, it is tempting to speculate that HCV-mediated downregulation of CD81 is involved in viral tumorigenesis." (PMID 38357447, 2024). "Finally, translocation of p65 in CD81-negative hepatoma cells was markedly induced upon stimulation with TNFα or PMA." (PMID 38357447, 2024). "Therefore, we used human hepatoma cell lines (Lunet N) lacking endogenous CD81 and expressed wildtype or C-terminally hemagglutinin- (HA) tagged CD81 in these cells." (PMID 30024968, 2018). "However, hepatoma cells expressing N-Moesin-GFP, a dominant negative mutant lacking the C-terminal actin-binding domain, showed a reduced ability to spread in response to CD81 ligation." (PMID 24662676, 2014). "Taken together, these results show that formation of heterokaryons between Huh-7.5 replicon cells and human hepatic, human non-hepatic and mouse hepatoma packaging cell lines rescued virus production and that produced infectious particles utilize CD81 during infection." (PMID 21552323, 2011). "As expected, Ctrl particles failed to infect human hepatoma cells, while particles decorated with VSV-G equally transduced hepatoma cells with and without CD81." (PMID 35612284, 2022). "Neither CAPN5 nor CBLB affected surface expression of SCARB1, CD81, CLDN1 and OLCN on human hepatoma cells." (PMID 30024968, 2018). "Comparable DC values for AcGFP-tagged CD81 and SR-BI were observed in non-polarized PHH and two independent hepatoma cell lines, Huh-6 and Huh-7.5." (PMID 23126643, 2013). "Consistent with the observation that these cell lines already express the necessary levels of the four HCV entry factors, over-expression of CD81, SR-BI, CLDN1 or OCLN individually or in combination did not significantly increase HCVpp or HCVcc entry in any of the hepatoma cell lines." (PMID 22273112, 2012). "CD81 chimeras, but not wild-type CD81, could internalize recombinant E2 protein and E2-enveloped viral particles from the serum of HCV-infected patients into Huh7 hepatoma cells." (PMID 15836798, 2005).
breast carcinoma (62 papers, 2010 to 2026). "The re-secreted wnt11-associated CD81+ exosomes then promote breast cancer motility via Wnt-related signaling." (PMID 38845751, 2024). "The increase in CD81 expression was significantly associated with clinical stage lymph node metastasis, and overall survival rate in patients with breast cancer." (PMID 36979448, 2023). "In breast cancer, CD81+ exosomes released by fibroblasts have been implicated in promoting the migration of breast cancer cells through the interaction of CD81 and Wnt11." (PMID 38136327, 2023). "CD9/CD81 also regulate α3β1 integrin, loss of these two tetraspanins impairs breast cancer spreading, motility, and disrupts its association with PKCα in a CD151-independent manner." (PMID 29946318, 2018). "Moreover, F11R/JAM-A was implicated in inhibition of TNBC breast cancer cell line MDA-MB-231 invasion by an antibody targeting the tetraspanin CD81." (PMID 37563645, 2023). "Thus, in human breast cancers, tumors with signatures of high CD81+CD63+EVs are more pro-inflammatory and associated with better clinical outcomes." (PMID 34503207, 2021). "In a gene expression study, data set from human breast cancers showed that CD81 was significantly upregulated in the stroma associated with breast cancer compared with control breast tissue, suggesting that CD81 may also have a role in the cancer associated in human breast cancer." (PMID 25682864, 2015). "In contrast, for sEVs from MCF-7 cells derived from breast cancer metastasis, there was a 1.5-fold higher abundance of CD81 than CD63 (p < 0.001)." (PMID 40411659, 2025). "The expression of CD81 in melanoma in humans was shown to promote tumor growth and metastasis, and knockdown of human CD81 in osteosarcoma and breast cancer cells reduced tumor progression and dissemination." (PMID 38280104, 2024). "Alternatively, as a prototype of pan‐EV capture, a mixture of biotinylated antibodies against human CD9 and CD81 were used to immobilise EVs from SKBR3 breast carcinoma cells onto a black streptavidin‐coated 96‐well plate." (PMID 39221546, 2024). "For instance, breast cancer animal models have established that breast cancer cells (BCCs) receive CD81+ exosomes from fibroblasts and later re-secrete them." (PMID 38845751, 2024). "The biosensor is constructed based on the signal modification that occurs when anti-CD81 recognizes CD-81 on the lipid membranes of small extracellular vesicles (EVs) from breast cancer." (PMID 38139054, 2023). "We then utilized three methods, immunofluorescence staining via CellSearch, flow cytometry, and RNA sequencing data analysis to further examine the CD81 expression in the CTCs isolated from patients with breast cancer." (PMID 36193887, 2022). "To determine if CD81 regulates breast cancer metastasis like CD44, we assessed the clinical relevance of CD81 expression in human breast tumors and CTCs." (PMID 36193887, 2022). "Combining machine learning and experimental investigation, here we report CD81, a tetraspanin transmembrane protein known to be enriched in extracellular vesicles (EVs), as a newly identified driver of breast cancer stemness and metastasis." (PMID 36193887, 2022). "Breast cancer-associated fibroblast-derived exosomes are enriched in tetraspanins, such as CD63, CD81, and CD82, whereas only CD81 is responsible for the transport of Wnt 11 cargo to exosomes." (PMID 36611951, 2022). "In a similar context, an upregulation of CD81 was observed in breast cancer cells upon silencing CD9." (PMID 36010551, 2022). "Fibroblast-secreted CD81-positive exosomes enhance the metastatic potential of breast cancer cells by regulating their motility." (PMID 34824296, 2021). "In breast cancer, for example, CD81-positive exosomes derived from CAFs promotes breast cancer cell motility and metastasis." (PMID 33899109, 2021).